TRIM64C (tripartite motif containing 64C)
Tractability: No criterion of Open Targets' tractability assessment is met for any kind of drug.
Gene: Protein-coding gene on chromosome 11 (49,053,714 to 49,059,112, reverse strand). Ensembl gene ENSG00000214891.
Gene Ontology:
Molecular function: ubiquitin protein ligase activity; zinc ion binding
Biological process: innate immune response; regulation of gene expression
Cellular component: cytoplasm
Genetic constraint (gnomAD): Loss-of-function variants: 22 observed, 27.98 expected, observed/expected ratio (o/e) 0.79, 90% interval 0.56 to 1.12. The upper end of that interval is the gene's LOEUF score, 1.12, which puts it in group 4 of 6, group 1 being the genes least tolerant of losing a copy. Missense variants: 460 observed, 493.77 expected, observed/expected ratio (o/e) 0.93, 90% interval 0.86 to 1.01. Synonymous variants: 204 observed, 173.6 expected, observed/expected ratio (o/e) 1.18, 90% interval 1.05 to 1.32.
Homologues: Orthologues: chimpanzee TRIM64C (97% identical). Paralogues in human: TRIM64 (91% identical), TRIM64B (91% identical), TRIM43 (47% identical), TRIM43B (47% identical), TRIM51 (46% identical), TRIM49 (45% identical), TRIM49C (45% identical), TRIM49B (45% identical), TRIM49D1 (43% identical), TRIM49D2 (43% identical), TRIM51G (43% identical), TRIM77 (41% identical), and 68 more.